ATRX (ATRX chromatin remodeler)
Diseases named in the same sentence as ATRX in open-access papers (continued):
Sharing a sentence is not in itself a finding about the gene and the disease.
tumor (continued). "A significant upregulation of ATRX, OLIG2, and downregulation of IDH2 at protein level was observed in GBM tumor samples compared to normal tissues, with p-values indicating statistical significance (**** p < 0.0001; *** p < 0.001)." (PMID 40282990, 2025). "By IHC, the tumor demonstrated diffuse positivity to synaptophysin, PLAP negativity, retained INI-1, focally retained ATRX expression, and focally retained nuclear expression of SMARCA4." (PMID 41353556, 2025). "Both tumor suppressor genes, DAXX and ATRX were found to affect 46% of all cases, with a higher prevalence in primary tumors with evidence of metastases." (PMID 41350422, 2025). "A heatmap was generated to depict the expression profiles of ATRX, OLIG2, MGMT, and IDH2 in normal and tumor tissues, using Log2(TPM+1) for scaling." (PMID 40282990, 2025). "Other tumour driver genes (NF1, ATRX, PIK3R1, SPTA, and PIK3CA) marked by IntOGen,54 were also found among the top 12 mutated genes." (PMID 41292185, 2025). "If the average F1 score improved by more than 5%—as observed for genes like BRAF, ATRX, and NRAS— selected tumour types were utilized for downstream analysis." (PMID 40775769, 2025). "Boxplots depict the protein expression levels (Z-values) of ATRX, OLIG2, MGMT, and IDH2 in normal tissue samples (n = 10, blue) and primary tumor samples (n = 99, red)." (PMID 40282990, 2025). "One group specifically demonstrated that ATRX-null cancers were highly-sensitive to HSV oncolytic viruses, providing firm evidence that this approach is valid and promising in these tumours." (PMID 40748226, 2025). "With the development of medicine, how ATRX mediates ALT, affects immune functions, epigenetic and its role in tumor development will be studied in the near future." (PMID 39479502, 2024). "The present study suggests that ATRX expression is a favorable prognostic indicator of overall survival and metastasis-free survival in patients with STS, even after controlling for tumor grade and size." (PMID 38741704, 2024). "A total of six (23.1%) patients in cohort A2 and all patients in cohort C tested positive for at least one of the selected biomarkers of ARID1A, ATRX/DAXX, ATM, as assessed in liquid and/or tumour biopsies." (PMID 38287179, 2024). "Losing ATRX or DAXX in addition to ALT positivity correlates with chromosome instability, higher tumour grading, and unfavourable prognosis in PanNET patients." (PMID 37296979, 2023). "However, one mechanism behind ATRX-driven tumours could be their effect on telomere length." (PMID 35382567, 2022). "Therefore, finding a PPGL carrying somatic mutations in NF1 and ATRX may not be unexpected, and warns of the malignant potential of the tumour carrying the ATRX mutation." (PMID 36760809, 2022). "We then injected the control and ATRX shRNA knockdown 143B cells s.c. in SCID-beige mice and monitored tumor growth rates over time." (PMID 36073547, 2022). "The independent clinical utility of assessing for ATRX status by immunohistochemistry in adults is unclear, especially considering that sequencing and/or methylation profiling would typically be required to confirm less common tumor diagnoses in the IDH-wt setting that may harbor ARTX alterations." (PMID 36397144, 2022). "Losing ATRX or DAXX, and ALT positivity correlates with chromosome instability, higher tumour grading, and unfavourable prognosis in PanNET patients." (PMID 36010860, 2022). "Similar to the supratentorial tumor cells, these tumor cells were positive for GFAP, SOX2, and ATRX." (PMID 34587990, 2021).
tumor (continued). "Therefore, classification by ATRX IHC alone might mislead the diagnosis of this tumor lineage." (PMID 34020723, 2021). "Well in line with histology, the tumor showed expression of both glial (e.g. GFAP) and neuronal markers (e.g. synaptophysin) with pathological expression of CD34 and retained ATRX expression." (PMID 32451719, 2020). "It has been observed in a number of studies that PML expression is completely or substantially lost, via unknown mechanisms, in many tumor types that are not known to be ATRX-deficient, and a more extensive survey of PML expression in cancer could potentially reveal many more." (PMID 30745338, 2019). "Among these, we validated and characterized ATRX, a SNF-2 type chromatin remodeler, due to its previously defined functions and its known role as tumor suppressor." (PMID 31180492, 2019). "In this type of tumours, a consistent correlation between ALT phenotype and inactivation of either ATRX or DAXX has been reported; however, ALT-positive cases that preserve expression of ATRX and DAXX indicates the presence of other activators." (PMID 29751586, 2018). "CtDNA from Patient F contained one SNV in the ATRX gene (3.53% of reads) and one SNV in the DLG2 gene (0.79% of reads) that matched tumor specific aberrations." (PMID 29560102, 2018). "Interestingly, ATRX mutations in NB and several other cancer types are associated with a telomerase-independent telomere maintenance mechanism known as alternative lengthening of telomeres (ALT), which is believed to be suppressed by wild-type ATRX in ALT-negative tumours." (PMID 29642598, 2018). "The resected tumor specimen was stained negatively for IDH1R132H and positively for ATRX." (PMID 41236163, 2026). "Nevertheless, we see how molecular phenotypes can segregate in overall survival, with certain tumor clusters, such as those without ATRX alteration, having a median survival of over three times that of tumors with CDKN2A/B alteration." (PMID 39584448, 2025). "Differential expression of small-RNA from TERT altered and ATRX altered tumours with non-metastatic primary tumours revealed down-regulation (adj." (PMID 40097403, 2025). "In summary, the patterns of DAXX and ATRX expression varied between non-malignant samples and tumour tissues in the prostate." (PMID 41472189, 2025). "In contrast, it shows a negative correlation with ATRX, a gene linked to TMZ resistance, and also with tumour‐growth‐promoting genes like BRAF and MET." (PMID 40662483, 2025). "This context dependence underscores that ATRX/DAXX loss is not intrinsically protective or detrimental, but its outcome is shaped by the tumor’s replication dynamics and genomic environment." (PMID 41148828, 2025). "Moreover, consistent with a role for ATRX, HNF4A and CDX2 in maintaining lineage fidelity and suppressing squamous-like plasticity, we observed low expression of these proteins in tumours containing LY6D+ cells." (PMID 40468074, 2025). "p < 0.05, log fold-change > 1.5) in both TERT altered and ATRX altered tumours relative to non-metastatic primaries." (PMID 40097403, 2025). "We first asked whether the relationship among ATRX, HNF4A, CDX2 and LY6D expression identified in our mouse model exists in human tumour samples." (PMID 40468074, 2025).
tumor (continued). "Contrasting the TERT and ATRX-altered tumours to non-metastatic tumours we found 1,152 and 1,448 differentially expressed genes, respectively." (PMID 38978571, 2024). "Among other immunostains not shown, ATRX nuclear expression was retained in all tumor cells, and none of the tumor cells were positive for IDH1 R132H mutant protein, napsin, NKX3.1, CD45, synaptophysin, INSM1, SOX10 protein, p40, CDX2 protein, PSAP, or PSA." (PMID 38845695, 2024). "All HN-PG/non-chromaffin tumours (defined by transcriptional profile) were excluded given the absence of TERT/ATRX alterations in these tumours." (PMID 38978571, 2024). "Therefore, it is reasonable to claim that in a progressing virtual tumour, the wild-type, TERT-rearranged, and ATRX-inactivated clones behaved identically on average." (PMID 39715281, 2024). "Indication of long tumor telomeres in the absence of ATRX aberrations was noted for cases 32R2B and 66R3A/C, while case 77R0A presented long telomeres in both tumor and corresponding normal." (PMID 38136279, 2023). "Naturally, it is no coincidence that the ATRX is now one of the most studied tumor suppressors in a variety of human cancers." (PMID 37373974, 2023). "We do not yet know the mechanism or significance of these large chromatin domain effects, but suggest they may account for some of the tumor-suppressor functions of DAXX and ATRX." (PMID 36028493, 2022). "The impact of ATRX and DAXX alterations on telomeric content was proportional to tumor purity." (PMID 35227290, 2022). "In addition to these genes, they determined that including ATRX knockdown via shRNA resulted in more circumscribed tumors after 4 months, and further addition of PDGFRA to the IUE model shortened the period of tumor growth to 21 days." (PMID 35978801, 2022). "The inactivation of DAXX/ATRX complex has been related to chromosomal instability and correlated with alternative lengthening of telomeres (ALT), as a senescence scape mechanism induced by telomere shortening in many tumours." (PMID 35626118, 2022). "BRAF, ATRX, IDH1, and CDKN2A showed significant SNV alterations in most tumour types." (PMID 36186436, 2022). "ATRX IHC for 7 of the 28 cases demonstrated ambiguous staining with variability of labeling across tumor cells and internal control non-neoplastic cells, and were considered uninterpretable; these cases were excluded from further analysis." (PMID 36397144, 2022). "We found, after correcting for tumor volume and location, correlations between the expression level of CD3 or IDH-1 and psychomotor speed; IDH-1, BDNF, ATRX, CK2Beta, GAT-3, NLGN3, SRF, or EAAT1 and memory performance, and P-STAT5b, NLGN3, CK2Beta, or IDH-1 and executive functioning." (PMID 35148403, 2022). "DAXX/ATRX immunohistochemistry staining in tumor cells is used as a tissue-based biomarker in non-metastasized settings, especially G2 tumors with potential progressive behavior." (PMID 35326628, 2022). "Besides, the clinicopathological features, including tumor grade, histology diagnosis, IDH status, 1p/19q codeletion, TERT promoter status, ATRX status, and MGMT promoter status, were also integrated." (PMID 36467068, 2022). "ATRX, CSDE1 and NF2 become the top SNA-based, CNA-based and mixed tumour suppressors, respectively." (PMID 35975235, 2022).
tumor (continued). "We identified SNVs in the exo-DNA that were not present in tumor DNA at onset of disease, in particular mutations of ALK, ATRX, NF1, and TERT genes, probably coming from other tumor sites." (PMID 33915956, 2021). "Alpha-like PanNETs were enriched for tumours with only MEN1 mutations (11/19), 8/19 α-like PanNETs were MEN1/DAXX/ATRX wild-type and none harboured MEN1 and DAXX/ATRX mutations." (PMID 33288854, 2020). "While important radiomics features for predicting ATRX and IDH mutations did not overlap completely, both predictive models relied heavily on diffusivity and T1 postcontrast image intensity within the tumor." (PMID 32678261, 2020). "In conclusion, the present study is the first to document a potential role for DAXX in mediating tumor progression and affecting outcome in metastatic HGSC, whereas ATRX expression does not appear to be informative in this tumor." (PMID 32533344, 2020). "In both works, tumor subgroups and mutations in MEN1, DAXX/ATRX, or the mTOR pathway genes did not associate." (PMID 30657883, 2019). "It is noted that some well-established associations like mutations in ATRX and DAXX (death-domain associated protein) for ALT as well as TERT promoter mutations for telomerase-positive cells are absent in many tumor samples." (PMID 29776332, 2018). "In NBLs, the TERT rearrangements were almost mutually exclusive with MYCN and ATRX (associated to another TMM, ALT), stratifying them in two groups of NBLs with very high risk, reinforcing the concept that tumours do not present multiple TMM simultaneously." (PMID 29751586, 2018). "The tumor cells demonstrated absence of ATRX immunostaining with intact staining in entrapped non-neoplastic neurons and endothelial cells, consistent with ATRX loss." (PMID 28699883, 2017). "Regarding protein loss (negative immunohistochemical staining results), ATRX loss in primary tumours was more common in A and AA than in pGBM, whereas MGMT loss was not significantly different among all tumour grades." (PMID 29026176, 2017). "The primary tumor of HGG15 had no detectable driver SNVs, however, it acquired an ATRX frameshift mutation as well as a RAD50 missense mutation at recurrence." (PMID 29084603, 2017). "We did not observe any correlation between PTEN, MEN1 and DAXX/ATRX alterations (not shown), neither between DAXX/ATRX loss and the initial grade of the tumor (p=0.093)." (PMID 28454119, 2017). "Additional immunostains revealed that the tumor cells had intact/retained expression of ATRX protein and were negative for IDH1-R132H mutant protein." (PMID 28699883, 2017). "Together, these findings culminated in the authors recommending assessment of both IDH and ATRX status and sequencing for both IDH1/2 and H3F3A for any age group when a tumor is found to have ATRX loss and lacking IDH1/2 mutations by immunohistochemistry." (PMID 29034211, 2017).
tumor (continued). "The tumor was negative for IDH1 p.R132H mutant protein expression with retained ATRX expression." (PMID 41736408, 2026). "The tumor was negative for IDH1 mutant protein expression and loss of ATRX expression." (PMID 40182052, 2025). "Although the MAX mutation is classified as type C2, including RET, NF1, TMEM127,H-RAS and ATRX, which belongs to the SWI/SNF family of chromatin remodeling proteins, as their upregulation will activate the PI3K/AKT and RAS/MAPK signaling pathways resulting in tumor formation." (PMID 39279998, 2024). "This implies that ATRX losses, which lead to an alternative lengthening of telomeres, may not be sufficient on their own to drive tumor formation but may complement mutant IDH1 expression, suggesting their potential functional synergism." (PMID 39160568, 2024). "However, metastasis in the absence of TERT/ATRX alterations was also evident in three metastatic tumours for two patients (E158, E159)." (PMID 38978571, 2024). "Interestingly, while it is also known that a larger primary tumour is associated with metastatic risk, only patients with TERT-altered tumours had larger primaries when contrasting to patients without TERT/ATRX alterations (Two-sided students t-test, p<0.05)." (PMID 38978571, 2024). "In addition, higher expression of ATRX, DDX3X, KDM5C and KDM6A was observed in female patients, indicating that tumor-suppressor genes that escape from X-inactivation may contribute to HCC sex bias." (PMID 36118521, 2022). "IDH-mutant tumours with non-conclusive ATRX staining were excluded from the calculation." (PMID 34165590, 2021). "Its tumor suppressive function has so far been related to its role in the alternative lengthening of telomeres (ALT) mechanism, which is a way to elongate telomeres without telomerase activation, inducing genome instability and leading to a poor prognosis of ATRX-altered tumors." (PMID 33946962, 2021). "Notably, all the DAXX/ATRX-negative samples expressed ARX, confirming the α-like tumour susceptibility for these mutations." (PMID 33288854, 2020). "To ascertain that these cells were tumoral and not cells of the tumour environment, we performed double labelling for pSTAT3 and proteins which are frequently altered in DLGG, namely the mutated form of IDH1 (R132H) and loss of ATRX." (PMID 32218467, 2020). "Interestingly, ATRX mutations and MYCN amplification have never been observed in the same NB tumor, suggesting a potential synthetic lethal condition." (PMID 33628735, 2020).